SOD1 (superoxide dismutase 1)
Diseases named in the same sentence as SOD1 in open-access papers (continued):
Sharing a sentence is not in itself a finding about the gene and the disease.
glomerulosclerosis (6 papers, 2013 to 2025). A hardening of the kidney glomerulus caused by scarring of the blood vessels. "Histologically, the extent of glomerulosclerosis and tubular atrophy, the amount of collagen deposition, interstitial fibrosis, inflammatory monocyte infiltration, and expression of transforming growth factor beta 1 (TGF-ß1), and superoxide dismutase 1 (SOD-1) were examined." (PMID 32015680, 2020).
hyperhomocysteinemia (6 papers, 2015 to 2024). A serious metabolic condition caused by mutations in the MTHFR gene, medications, or nutritional deficiency. "Unlike previous studies, our experimental design included a genetic approach to alter superoxide levels by using superoxide dismutase 1 (SOD1)-deficient mice fed a high methionine/low folate diet to produce hyperhomocysteinemia." (PMID 28414812, 2017). "In contrast, a partial deficiency of SOD1 in Sod1+/- mice was sufficient to drive the phenotype only in the setting of diet-induced hyperhomocysteinemia." (PMID 28414812, 2017). "In this study, we utilized SOD1-deficient mice to determine the pathophysiological importance of superoxide-derived ROS in the cerebral vascular consequences of diet-induced hyperhomocysteinemia." (PMID 28414812, 2017). "Effect of hyperhomocysteinemia on cerebral arteriolar composition in SOD1-deficient mice." (PMID 28414812, 2017). "Wild type (Sod1+/+), heterozygous (Sod1+/-), and homozygous (Sod1-/-) littermate mice were fed either a control diet or a HM/LF diet to produce hyperhomocysteinemia." (PMID 28414812, 2017). "The degree of vessel hypertrophy in Sod1+/- mice fed the HM/LF diet was equally as severe as that detected in Sod1-/- mice fed either diet, suggesting a threshold effect of Sod1 genotype in the presence of hyperhomocysteinemia." (PMID 28414812, 2017). "On the basis of our study and previous findings, we put forward a hypothesis that hyperhomocysteinemia causes increased ROS production by modulating NOX4 and SOD1 activity in the RVLM." (PMID 29098089, 2017). "Moreover, we find that the expression of NOX4 (a subtype of NADPHase) is significantly increased, whereas SOD1 was decreased in hyperhomocysteinemia rats compared to vehicle groups." (PMID 29098089, 2017). "The hyperhomocysteinemic response to the HM/LF diet was not altered by deficiency of SOD1, which suggests that dysregulation of superoxide is a consequence, rather than a cause of hyperhomocysteinemia." (PMID 28414812, 2017). "We chose to target SOD1 in this study because it is the most abundant cellular isoform of SOD in vascular tissues, it is a direct regulator of superoxide, and superoxide-derived ROS have been proposed as mediators of vascular dysfunction and vascular structural abnormalities in hyperhomocysteinemia." (PMID 28414812, 2017).
muscle atrophy (6 papers, 2020 to 2023). The loss of muscle tissue due to inactivity or disease. "Muscle atrophy in G93A*SOD1 mice was associated with increased and differential expression of mutant-SOD1 across myofibers and increased MuRF1 protein level." (PMID 38516553, 2023). "The delay in the presentation of muscle atrophy is observed despite alpha motor neuron loss being evident within a few months after Sod1 deletion." (PMID 32886862, 2020). "The adeno-associated virus (AAV)-mediated CRISPR system was applied to disrupt SOD1, leading to decreased expression of SOD1 protein in spinal cord and reduction of muscle atrophy in mice." (PMID 34194298, 2021). "Muscle atrophy has been observed in both the classical mouse model SOD1-G93A and in the transgenic mouse model, in which the mutant SOD1 is expressed only in skeletal muscle (MLC/SOD1-G93A) and not in the neurons." (PMID 35159225, 2022).
respiratory failure (6 papers, 2014 to 2025). The significant impairment of gas exchange within the lungs resulting in hypoxia, hypercarbia, or both, to the extent that organ tissue perfusion is severely compromised. "Mutations of conserved residues of SOD1 were significantly associated with shorter survival times and shorter time between the disease onset and respiratory failure in ALS patients." (PMID 34996976, 2022). "The relationship between mean age at respiratory failure death in patients with different SOD1 mutations and changes in the stability of their mutant SOD1 proteins showed a good fit with a linear regression model of logarithmically transformed Eq." (PMID 25400549, 2014). "3, suggests that the variability in mean survival time among patients with different SOD1 mutations is largely dependent on the differences in extension time at respiratory failure death (tER)." (PMID 25400549, 2014). "Respiratory failure due to progressive impairment of the neuromuscular system has been reported as a main cause of death in ALS and the major trigger for premature death in SOD1 G93A mice." (PMID 29084947, 2017). "The absence of bulbar symptoms, respiratory failure, and the presence of sensory impairments, along with the electrophysiological findings, collectively distinguishes SOD1-IPN from ALS." (PMID 39932579, 2025).
kidney injury (5 papers, 2018 to 2023). Trauma to the kidney. "Another possible explanation of our findings is that SOD1 is upregulated following acute kidney injury as a damage response mechanism." (PMID 37821813, 2023).
lupus (5 papers, 2006 to 2025). "Oxidative stress due to SOD1 deficiency induces a lupus phenotype in C57BL/6 mice and exacerbates hemolytic anemia in NZB mice." (PMID 39061948, 2024). "coli protein in the liver and normalized the enhanced expression of TLR-7, p-NFκB/NFκB, SOD1 and SOD2 induced by lupus." (PMID 41595543, 2025).
mental disorder (5 papers, 2017 to 2026). A disease that has its basis in the disruption of mental process. "These include five genes encoding proteins that aggregate in neurodegenerative and/or mental illness: CRMP1 (also called DPYSL1), DISC1, MAPT (encoding the Tau protein), PRKN (also called PARK2, encoding Parkin), and SOD1." (PMID 42194081, 2026). "Nevertheless, the important role of oxidative stress in the development of many mental disorders should not be ignored—the increased gene expression levels could correspond to an increased need for the enzymatic activity of SOD1 due to increased oxidative stress." (PMID 41465140, 2025).
muscular atrophy (5 papers, 2010 to 2021). "SOD1 KO mice are considered a useful model to investigate the association between an increase in ROS production and muscular atrophy, but responses specific to this model are also observed." (PMID 26798428, 2016). "The down-regulation of this important antioxidant in response to TNF-α treatment in our microarray data suggests a possible link between the regulation of Sod1 and TNF-induced muscular atrophy." (PMID 20967264, 2010).
myeloid leukemia (5 papers, 2011 to 2023). A clonal proliferation of myeloid cells and their precursors in the bone marrow, peripheral blood, and spleen. "It was recently shown that in U937 human myeloid leukemia cells, increased exposure to TNFα caused a down regulation of SOD1." (PMID 21655261, 2011). "SOD1 regulates cell death and differentiation in myeloid leukemia cell lines K562, MEG-01, TF-1, and HEL." (PMID 35056649, 2022). "Moreover, it was reported that SOD1 inhibition decreases cell growth and induces cell death in myeloid leukemia cells." (PMID 36708053, 2023). "U937 human myeloid leukemia cells were treated with different doses of PDTC and SOD1 mRNA levels were determined by real- time PCR analysis." (PMID 25996379, 2015). "Similarly, the inhibition of the free radical scavenger Cu, Zn superoxide dismutase (SOD1), which is co-imported into mammalian peroxisomes with a copper chaperone, led to cell proliferation arrest and the promotion of cell death in myeloid leukemia cells." (PMID 31398943, 2019).
myeloma (5 papers, 2014 to 2024). "ATN-224 was reported to exhibit anticancer activity via inhibition of SOD1, which resulted in increased superoxide levels and subsequent induction of ROS-dependent apoptosis in multiple myeloma cells." (PMID 37371889, 2023). "A similar cytotoxic mechanism has been ascribed to bortezomib, and the emergence of resistance in myeloma has been linked to upregulation of antioxidant enzymes, notably SOD1." (PMID 37315065, 2023).
nasopharyngeal carcinoma (5 papers, 2018 to 2024). A carcinoma arising from the nasopharyngeal epithelium. "Therefore, clarifying the function and underlying mechanism of SOD1 in nasopharyngeal carcinoma development has become a core issue in the treatment of NPC." (PMID 29891006, 2018). "The Sod1 knockout mice were characterized by lipid accumulation in liver and abnormal circulating lipid profiles, and the inhibition of SOD1 function in nasopharyngeal carcinoma connived the accumulation of lipid droplets." (PMID 32559230, 2020). "In this study, we first investigated how the disruption of SOD1 affects the antioxidant defence system and nasopharyngeal carcinoma cell growth." (PMID 29891006, 2018). "The knockdown of SOD1 in nasopharyngeal carcinoma cells reduced its growth and induced apoptosis." (PMID 35056649, 2022). "A significant upregulation of SOD1 in nasopharyngeal carcinoma (NPC) tissue is observed and high SOD1 expression is a predictor of poor prognosis and is correlated with poor outcome, indicating that SOD1 is a potential prognostic biomarker and a promising target for NPC therapy." (PMID 35978820, 2022). "SOD1 is overexpressed in many types of cancer, including non-small cell lung cancer (NSCLC), breast cancer, or nasopharyngeal carcinoma." (PMID 35056649, 2022).
selenium deficiency (5 papers, 2018 to 2024). A nutritional deficiency disease resulting from inadequate selenium levels in the body, which can lead to impaired function of selenoproteins essential for antioxidant defense and thyroid hormone metabolism. "As these seleno‐dependent antioxidants adapted to maternal selenium deficiency, we examined if this altered the non‐seleno‐dependent antioxidants superoxide dismutases 1 and 2 (Sod1/2)." (PMID 33769708, 2021). "On the other hand, spot 2202 (SOD1) exemplifies the opposite situation, where a downregulation of the protein occurred during replicative senescence (−118%) and selenium deficiency (−174% in senescent cells)." (PMID 29361692, 2018). "Sod1 and Sod2 mRNA were unaffected by maternal selenium deficiency." (PMID 33769708, 2021). "Next, we examined if non‐seleno‐dependent antioxidants were dysregulated in the kidneys of offspring exposed to maternal selenium deficiency and demonstrated no changes in Sod1 or Sod2 mRNA." (PMID 33769708, 2021).
Sensory neuropathy (5 papers, 2022 to 2025). Peripheral neuropathy affecting the sensory nerves. "The only exception is represented by SOD1 mutated ALS patients, in which sensory neuropathy seems to be more frequent than other ALS subtypes." (PMID 37610446, 2023). "Sensory neuropathy in ALS may be associated with a spinal onset and might be more frequent in SOD1 patients." (PMID 37610446, 2023).
sickle cell anaemia (5 papers, 2019 to 2026). "Interestingly, genetic variations in SOD1-5′AS gene have been linked to cancer and sickle cell anemia." (PMID 30610612, 2019).
skin atrophy (5 papers, 2014 to 2021). The degeneration and thinning of the epidermis and dermis. "Cu-Zn superoxide dismutase (Sod1) loss causes a redox imbalance as it leads to excess superoxide generation, which results in the appearance of various aging-related phenotypes, including skin atrophy." (PMID 25333617, 2014). "Further analysis should be needed to clarify the beneficial effect of other RSV derivatives in MSE on skin atrophy in Sod1−/− mice." (PMID 26180586, 2015). "The skin of the Sod1−/− mice was significantly thinner than that of the Sod1+/+ mice, confirming that skin atrophy had occurred in the Sod1−/− mice." (PMID 25333617, 2014). "The administration of a low concentration of PAPLAL also improved the skin atrophy observed in the Sod1−/− mice (the thickness of the epidermis and dermis were increased by 42.0% and 21.1%, respectively) compared with that seen in the Sod1−/− mice treated with vehicle." (PMID 25333617, 2014). "To investigate skin atrophy-preventing mechanism of MSE and RSV on skin atrophy in Sod1−/−, we analyzed expression patterns of type I collagen and age-related genes in skin." (PMID 26180586, 2015).
sleep disorder (5 papers, 2022 to 2025). A change from the patient's baseline sleeping pattern, in the hours slept and/or an alteration/dysfunction in the stages of sleep. "ATP5B, COX5A, GAPDH NDUFV2, SOD1, UQCRC1, and UQCRC2 have been reported as sleep deprivation and sleep disorder-related genes, and these studies have contributed to the development of candidate biomarkers for the diagnosis and treatment of plateau-induced sleep disorders." (PMID 36860517, 2023).
tendinopathy (5 papers, 2022 to 2026). "Mice deficient of an antioxidant enzyme, superoxide dismutase 1 (Sod1), showed degeneration in the supraspinatus tendon entheses, supporting that intracellular oxidative stress contributes to rotator cuff degeneration in tendinopathy." (PMID 35408931, 2022).
transient cerebral ischemia (5 papers, 2016 to 2024). "In gerbil hippocampus, after transient cerebral ischemia, LA treatment attenuated superoxide anion generation and lipid peroxidation by increasing the expression of SOD1 and SOD2." (PMID 32629814, 2020).
vivax malaria (5 papers, 2010 to 2025). "Liver enzymes are highly inducible by the activation of immune responses and ALT was also correlated with TNF and superoxide dismutase-1 (SOD-1) levels in another case series of vivax malaria." (PMID 26271921, 2015). "SOD-1 was a more powerful predictor of disease severity than TNF-alpha in individuals with different clinical presentations of vivax malaria." (PMID 20386593, 2010). "Although investigations analyzing more patients with broader clinical outcomes are necessary, SOD-1 plasma protein levels seems to represent a useful marker in predicting vivax malaria severity based on the oxidative response status." (PMID 20386593, 2010). "The present work shows that the plasma level of SOD-1 is a surrogate marker of severe vivax malaria in a population from the Brazilian Amazon, in which P. vivax infection is highly endemic." (PMID 20386593, 2010). "In predicting severe vivax malaria, SOD-1 levels exhibited higher sensitivity than TNF-alpha (80% vs. 56%, respectively; p<0.0001; likelihood ratio: 7.45 vs. 3.14; p<0.0001)." (PMID 20386593, 2010). "SOD-1 is a powerful predictor of disease severity in individuals with different clinical presentations of vivax malaria." (PMID 20386593, 2010). "Plasma SOD-1 has been reported earlier as a surrogate marker of vivax malaria severity." (PMID 27090372, 2016). "Furthermore, SOD-1 has a higher sensitivity than TNF-alpha in predicting severe vivax malaria, indicating also a higher likelihood ratio to discriminate this clinical condition." (PMID 20386593, 2010). "Thus, we investigated individuals from an Amazonian region highly endemic for vivax malaria with the goal of predicting infection severity by measuring superoxide dismutase-1 (SOD-1) plasma levels." (PMID 20386593, 2010). "The role of SOD-1 in vivax malaria could be either protective or deleterious with regard to the infection outcome." (PMID 20386593, 2010). "SOD-1 protein levels were more effective at predicting vivax malaria severity than TNF-alpha." (PMID 20386593, 2010). "Increased vivax malaria severity was associated with higher plasma levels of SOD-1 (P<0.0001), with similar trend being noted with regard to SOD activity (P<0.01 for linear trend; data not shown)." (PMID 20386593, 2010). "Here we tested whether plasma levels of SOD-1 could serve as a biomarker of severe vivax malaria." (PMID 20386593, 2010). "In an attempt to address if the plasma levels of both SOD-1 and TNF-alpha were useful to discriminate P. vivax from P. falciparum malaria, we compared plasma samples from individuals presenting with mild symptomatic vivax malaria and age matched individuals with symptomatic P. falciparum infection." (PMID 20386593, 2010). "In addition, the specific role of SOD-1 in the immunopathogenesis of severe vivax malaria was not explored in this study and is still being addressed by our group." (PMID 20386593, 2010).
amnesia (4 papers, 2014 to 2020). Pathologic partial or complete loss of the ability to recall past experiences ( AMNESIA, RETROGRADE) or to form new memories ( AMNESIA, ANTEROGRADE). "As another alkaloid, embelin (2,5-dihydroxy-3-undecyl-1,4-benzoquinone) notably improved the memory retention and recognition index in scopolamine-induced amnesia in rats by elevated expression of SOD1 and CAT as Nrf2 target genes." (PMID 33114450, 2020).
angina pectoris (4 papers, 2015 to 2023). The symptom of paroxysmal pain consequent to MYOCARDIAL ISCHEMIA usually of distinctive character, location and radiation. "Other researchers stated that in patients with unstable angina, there are diminished serum levels of 6-sulfatoxy melatonin and SOD1 associated with an increase of oxidized-LDL levels as a first step to the atherosclerotic process." (PMID 34683825, 2021).
bladder urothelial carcinoma (4 papers, 2011 to 2025). "It has been reported that the expression of CEBPD reduced cisplatin-induced ROS and apoptosis in bladder urothelial carcinoma cells by inducing Cu/Zn-superoxide dismutase (SOD1)." (PMID 36035213, 2022).
dilated cardiomyopathy (4 papers, 2012 to 2020). Cardiomyopathy which is characterized by dilation and contractile dysfunction of the left and right ventricles. "Lack of SOD2 gene in mouse germ line resulted in much greater and earlier retinal changes including photoreceptor degeneration compared to the SOD1 knockout mice; however, these mice died before weaning due to dilated cardiomyopathy." (PMID 22715395, 2012). "Conversely, there was no increase in SOD1, another ROS scavenger, suggesting a minor role for this enzyme similarly to human dilated cardiomyopathy." (PMID 32527005, 2020).
fetal growth restriction (4 papers, 2019 to 2023). A fetus that does not grow beyond the 10th percentile of conventionally accepted weight for gestational age. "Hence, fetal growth restriction was observed to increase the activity of SOD-1 in placentae as well as the lipid peroxidation in both placenta and umbilical cord plasma by augmenting the level of malondialdehyde, which is an end-product of the fatty acid oxidation." (PMID 36768564, 2023).
Gliosis (4 papers, 2011 to 2021). Gliosis is the focal proliferation of glial cells in the central nervous system. "Moreover, overexpression of ChgA in G37R SOD1 Tg mice accelerated the disease onset and gliosis, while misfolded SOD1 was detected in the cerebrospinal fluid of patients with familial ALS using antibodies specifically recognizing misfolded SOD1 species." (PMID 22072931, 2011).
hypoxic-ischemic encephalopathy (4 papers, 2018 to 2025). "Nevertheless, these neonates experience higher degrees of oxidative stress, which leads to severe hypoxic-ischemic encephalopathy, and overexpression of SOD-1 in mouse brains increases perinatal asphyxia-induced damage." (PMID 32816128, 2020). "In addition, DIM inhibited apoptosis and oxidative stress accompanying perinatal asphyxia through: downregulation of FAS, CASP-3, CAPN1, GPx3 and SOD-1, attenuation of caspase-9 activity, and upregulation of anti-apoptotic Bcl2 mRNA." (PMID 32816128, 2020).
insulinoma (4 papers, 2011 to 2023). "Studies utilizing overexpression of GPX1, SOD1 (Cu/Zn SOD), SOD2 (MnSOD), or SOD mimetic administration in insulinoma cell lines such as NIT-1 and INS-1 afforded protection from ROS and reactive nitrogen species (RNS) in vitro." (PMID 21647409, 2011).